XCL2 (X-C motif chemokine ligand 2)
Diseases named in the same sentence as XCL2 in open-access papers (continued):
Sharing a sentence is not in itself a finding about the gene and the disease.
cancer (continued). "Our study revealed a close relationship between XCL2 and immune checkpoint genes in various human cancers, confirming the hypothesis that XCL2 may enhance immunotherapeutic responses in cancer by synergizing with other known immune checkpoint inhibitors." (PMID 37905956, 2023). "Furthermore, we used scRNA-seq to characterize the landscape of XCL2 in different cancer cell subsets and found that XCL2 was highly enriched in immune cells, especially CD8+ T cells, NK cells, and macrophages." (PMID 37905956, 2023). "Furthermore, we analyzed the prognostic effect of XCL2 in 33 cancer types using univariate Cox regression analyses and Kaplan–Meier survival curves." (PMID 37905956, 2023). "However, the pathophysiological mechanisms of XCL2 protein in various disease conditions, particularly cancer, remain poorly understood." (PMID 37905956, 2023). "Like many other oncogenes, XCL2 acts as a key molecule in pan-cancer." (PMID 37905956, 2023). "Similarly, the pathophysiological mechanisms of the XCL2 protein in several disease conditions, particularly cancer, remain poorly understood." (PMID 37905956, 2023). "XCL2 plays a significant role in the development and progression of various cancers." (PMID 37905956, 2023). "In contrast, the expression of genes regulating immune cell trafficking (e.g., CXCL13, CXCL9, XCL2, CCL5), T-cell activation and clonal expansion (e.g., CD27, CD28, ICOS, IL21, IL2) were massively decreased in 9p21-loss tumors across multiple cancer types/subtypes." (PMID 34556668, 2021). "Additionally, we used the SangerBox platform to determine whether there was a correlation between XCL2 expression and the pathological stages of various cancers." (PMID 37905956, 2023). "Additionally, most pan-cancer samples had a much higher proportion of M1 macrophage marker iNOS-positive cells than para-cancerous tissues, indicating the potential involvement of XCL2 in the recruitment of M1 macrophages in the TME." (PMID 37905956, 2023). "Therefore, further studies are needed to confirm the complex role of XCL2 in pan-cancers." (PMID 37905956, 2023). "Preliminary research indicates that XCL2, like XCL1, is involved in the development and activation of cytotoxic T cells and the progression of malignant tumor growth." (PMID 37905956, 2023). "We demonstrated that high expression of XCL2 correlated strongly and positively with M1 macrophages and CD8 T cells in pan-cancer, whereas other cells (e.g., macrophage type M0, macrophage type M2, and CD4 T cells) showed inconsistent correlations." (PMID 37905956, 2023). "We found a positive correlation between XCL2 expression and CD8 + T cells and macrophages (especially M1 macrophages) in pan-cancer." (PMID 37905956, 2023). "Simultaneously, we found that the expression of FASN was correlated with various chemokines (e.g., XCL2 and CCL14) and chemokine receptors (e.g., XCR1 and CCR8) in different cancers." (PMID 36555243, 2022). "Further studies on the response to immune checkpoint inhibitor therapy have shown that responders exhibited higher XCL2 expression than non-responders in pan-cancer." (PMID 37905956, 2023). "CCL5, XCL1, XCL2, CCL17, CCL22, and CCL19 showed a positive correlation with DEF6 in most cancers, and DEF6 may function in regulating these chemokines in cancer." (PMID 36686789, 2022). "Among the remaining 8 DEGs (ADRA2A, P2RX6, XCL2, XCL1, CCL7, TRIM54, TNFRSF18 and SPOCK1), the expression of ADRA2A, the top one, in KIRC based on individual cancer is lower than the normal tissues, but patients with lower expressed ADRA2A have a better overall survival (OS)." (PMID 31159832, 2019). "Similarly, in human cancers, intratumoral CCL5, XCL1, and XCL2 transcripts closely correlate with gene signatures of both NK cells and cDC1 and are associated with increased overall patient survival." (PMID 29429633, 2018).
cancer (continued). "DNA methylation reduced XCL2 mRNA expression and was statistically correlated with KIRP, KIRC, THCA, SKCM, LGG, and TGCT, suggesting that DNA methylation of the XCL2 gene may determine the mRNA levels of XCL2 in cancers." (PMID 37905956, 2023).
XCL2 also shares sentences with these, for which no sentence is quoted: lung adenocarcinoma (3 papers); infection (2); alcohol (1); autoimmune disease (1); breast invasive carcinoma (1); co-infection (1); gastric cancer (1); Granuloma (1); head and neck squamous cell carcinoma (1); liver disease (1); psoriasis (1); skin cutaneous melanoma (1).